IL13 (interleukin 13)
Diseases named in the same sentence as IL13 in open-access papers (continued):
Sharing a sentence is not in itself a finding about the gene and the disease.
infection (continued). "WT mice displayed significant increases in Retnla, Il4, Il5, Il13, and Ccl11 (Eotaxin) mRNA expression following infection with N. brasiliensis, while Il25 and the mucin genes Muc5ac and Gob5 were not altered." (PMID 19381262, 2009). "Infection levels are mainly regulated by a major locus SM1, in 5q31-q33 region, which contains the genes encoding for the IL-4, IL-13, and Il-5 cytokines." (PMID 19471606, 2008). "As IgE and eosinophils are highly dependent on IL-4, Il-5 and IL-13, it was thought that protection against infection by Schistosoma would involve a Th2 immune response." (PMID 19471606, 2008). "However, the infection predominantly induces a Th2‐biased immune profile, characterized by elevated levels of IL‐4, IL‐5, IL‐10, IL‐23, and IL‐13, which appears to support parasite survival within the host." (PMID 41503693, 2026). "Concentrations of Th-2 cytokines (IL-4, IL-5, and IL-13) as well as expression all the genes (IL-4, IL-5, and IL-13) were found to be greater (p < 0.05) in resistant sheep on different days post infection." (PMID 41993907, 2026). "The frequency of IL-13+ ILC2s decreased 1 week after infection, when worm larvae migrated away from the intestinal lumen and temporarily took up residence close to the outer muscularis layer, where they might be shielded from tuft cell detection." (PMID 40074948, 2025). "Moreover, we found that the CD4 T helper 2 cytokine IL-13 was preferentially induced in the context of infection with modern lineages compared to ancestral lineages (median scaled responses 1.18 [modern] vs. 0.78 [ancestral])." (PMID 40162896, 2025). "Tm immunity is dose dependent: low egg doses (LD, ~20 eggs) generally result in TH1‐mediated adaptive responses and chronic infection, while high doses (HD, > 100 eggs) infection results in TH2 responses including IL‐13 production, the key cytokine effecting stroma‐mediated expulsion." (PMID 40944312, 2025). "Heterologous infection of wild-type mice significantly increased mRNA expression of Il4, Il5, Il13." (PMID 41573550, 2025). "Importantly, injection of anti-IL-13, at 2- and 4-days post CR infection, diminished local secretion of IL-10 and IL-22." (PMID 40591723, 2025). "HBoV1 infection increases the concentrations of IL-2, IL-4, IL-10, and IL-13 in patients." (PMID 39846742, 2025). "In accordance with the drainage of the upper SI shared between MLN and CLN, both sites comprised significantly elevated and similar frequencies of IL-4 and IL-13 competent Th2 cells during larval development (day 6 p.i.)and after transition to the patent stage of infection (day 14 p.i.)." (PMID 40092986, 2025). "Additionally, Type 2 cytokines such as IL-4 and IL-13 were also present in the primary infection mice at these two time points, and with significantly higher IL-5 expression at 7 DPC than all other groups." (PMID 41190814, 2025). "Eosinophils, basophils, and mast cells are known to play a key role in the initiation and regulation of Th2 responses; these cells may be promptly recruited to infection sites and draining lymph nodes in order to produce IL-4 and/or IL-13." (PMID 40150023, 2025). "This increase was still apparent for Il-13 10 days post Tg infection." (PMID 38950025, 2024). "Furthermore, it resulted in decreased levels of Th2 cytokines (IL-4, IL-5, and IL-13) after infection, while interferon γ levels remained largely unchanged." (PMID 38016013, 2024). "Infection with helminths activates a type 2 immune response aimed at expelling the invading helminth characterized by the release of type 2 cytokines, IL-4, IL-5 and IL-13." (PMID 39596084, 2024). "Taken together, these data suggest that mice with basophils deficient for IL-4 and IL-13 failed to control bacterial translocation into the blood during infection and this was not dependent on a lack of neutrophil activation." (PMID 38780542, 2024).
infection (continued). "However, compared to Tg infected animals, HpTg infected animals only had decreased levels of MLN Ifnγ and SI2 Il-10 at day 5 post Tg infection, despite increased Il-4 and Il-13 in the SI, PP, MLN and SPL." (PMID 38950025, 2024). "However, long-term infection drives the immune system towards a Th2 response with high levels of IL-4, IL-5, IL-13, and immunosuppressive IL-10 and TGF-β, leading to tolerance." (PMID 38817444, 2024). "We hypothesized that an IL-13-induced infection model of the intestines would reveal similar changes in mucus rheology." (PMID 38721267, 2024). "This protein binds and blocks IL-13, but also has HS-binding activity which has been proposed to tether p43 to the extracellular matrix, increasing survival of the protein at the site of infection." (PMID 39514278, 2024). "IL-13 and IL-5 genes were strongly up-regulated in animals with previous exposure to the infection." (PMID 38338687, 2024). "Indeed, during infection, IL‐13 has multiple host‐protective roles, including parasite expulsion and limiting bleeding." (PMID 39606183, 2024). "In addition to increased intestinal permeability, we observed increased bacterial 16S copies in blood of baso IL-4/IL-13 (−) mice relative to genotype controls following infection." (PMID 38780542, 2024). "This was accompanied by changes in cytokine profiles and parasite loads which were dependent on the cell type (CD4+ T, CD8+ T, NK, NKT and γδ T cells), the organ (SI, PP, MLN, SPL and liver), the time-point (day 5 and 10 post-infection) and the cytokine (IFNγ, IL-4, IL-10 and IL-13) studied." (PMID 38950025, 2024). "However, during the muscle stage of infection, there was a shift towards a Th2 response, characterized by the production of cytokines such as IL-4, IL-10, and IL-13, which were involved in regulating inflammation and tissue repair." (PMID 38166140, 2024). "As the infection progresses, a delicate shift occurs, characterized by a transition to adaptive immunity, guided by cytokines like interleukin-4 (IL-4), interleukin-5 (IL-5), and interleukin-13 (IL-13), promoting antibody production and T-cell responses." (PMID 38694310, 2024). "Moreover, after infection for 8–10 days, the nILC2s in the lung were significantly increased, with high expression of IL-13 and IL-5, as well as a small amount of IL-4." (PMID 37173731, 2023). "In addition, inoculation of birds with L. reuteri resulted in upregulation (P < 0.05) of the IL-13 expression in the ileum post CP-infection, compared to the other CP challenged groups." (PMID 38022592, 2023). "Interestingly, IL-13 can induce an alternative activation state in macrophages in the context of infection with F. tularensis LVS, resulting in enhanced intracellular replication and survival of bacteria." (PMID 36602520, 2023). "The infection of bacteria or viruses can trigger type I pro-inflammatory immune responses (e.g., IFN-γ, TNF-α, TH1 cells), whereas infection by helminths typically elicits a type II host resistance and tolerizing immune response (e.g., IL-4, IL-5, IL-13, TH2 cells)." (PMID 37789420, 2023). "The infection with Mtb increased the production of IL-10, IL-13, and IL-5." (PMID 37375056, 2023). "The pathogen infection stimulated pro-inflammatory responses with IL-13 expression." (PMID 37240767, 2023). "Additionally, there was a significant decrease production of 13.8-fold in IL-4, 21.3-fold in IL-5, and 12.6-fold in IL-13 at day 90, compared to the highest levels observed at 30 days of infection." (PMID 37691941, 2023). "However, NE severity is thought to be a result of excessive production of IL-1β, IL-13 and IL-17 cytokines during infection, a mechanism mediated via Th2 and Th17 cells." (PMID 38164397, 2023).
infection (continued). "This dynamic study of F. gigantica-infected buffalo serum cytokines has revealed that, in the early stages of both primary and secondary infection, Th2/Treg dominated response was induced; this was manifested in increases of IL-4, IL-5, IL-10, IL-13, and TGF-β and reduction of IFN-γ and IL-17." (PMID 37152685, 2023). "Increased levels of IL-4 and IL-13 in late-phase infection (12 wpi) were detected in serum; these exhibited synergy, which may be associated with M2 activation for damaged tissue repair." (PMID 37152685, 2023). "The M1-related cytokines, IFN-γ and TNF-α, increased and reached a peak at the 6th week post-infection (with IFN-γ higher than TNF-α), while the M2-related cytokines, IL-10 and IL-13, were boosted during the late stage of infection (with higher IL-10 than IL-13)." (PMID 36668953, 2023). "For group B, compared with pre-infection, the level of IL-13 increased at 0–4 wpi, followed by a decline at 5–6 wpi, and then increased at 10 and 12 wpi, among which significant increases were detected at 3 and 12 wpi (p < 0.05), while significant decreases were detected at 5 and 6 wpi (p < 0.05)." (PMID 37152685, 2023). "ARG1 is a cytoplasmic enzyme that is expressed in macrophages, bone marrow-derived suppressor cells, dendritic cells, and innate lymphoid group 2 cells in response to Th2-type cytokines (IL-4 and IL-13) and infection with pathogens related to other signaling factors." (PMID 36918848, 2023). "Despite these limitations, the present study was able to show that symptomatic P. falciparum infection is associated with increased levels of the cytokines IL-10, IL-13, IL-6, IFN-γ and IL-12p70 while asymptomatic infection is marked by increased levels of IL-10, IL-13, IL-22 and IL-12p70." (PMID 36787308, 2023). "Notably, although no obvious differences in the number or activation state of ILC2s were detected, we also found that the type 2 cytokine Il13 and the related alarmin Il33 were significantly up‐regulated after infection." (PMID 35018740, 2022). "We assume that the IL-4/IL-13 stimulation induced initial alterations in the skin samples that sufficiently alter the integrity of cell-cell junctions that allow the virus to reach its receptors and initiate infection." (PMID 35969080, 2022). "For instance, increased periodontal pathogen abundance will enhance the stimulation of TLRs, induce Th1 to secrete IL-2, IFN-γ, TNF-α to kill intracellular infection pathogens, and then induce Th2 to secrete IL-4, IL-5, IL-6, IL-13 to regulate humoral immunity and limit Th1 response." (PMID 35254118, 2022). "p43 can be detected in the caecal mucus of chronically infected mice (the caecum being the primary infection site during chronic infection), suggesting that tethering to mucus proteoglycans may enable p43 to sequester IL-13, thus promoting parasite survival." (PMID 36175934, 2022). "None of these studies have looked at the local effect these cytokines (IL-4 and IL-13) may have at the primary site of infection, the epidermis." (PMID 35456017, 2022). "Moreover, ILC2-producing IL-5 and IL-13 were markedly increased in PreF- and PreFAlum-immunized sero- compared to sero+ dams, suggesting that prior infection mitigated the ILC2 response following RSV challenge." (PMID 36268035, 2022). "Furthermore, at the protein level, we also confirmed that all four Th2 cytokines (IL-4, IL-6, IL-10, and IL-13) were progressively enhanced in both mouse and rat lungs during the late infection phase of AC." (PMID 35617354, 2022). "Intriguingly, after ex vivo infection of interleukin-4 (IL-4)/IL-13-treated skin, we observed infected cells supporting that Th2 responses already enabled the virus to overcome the protective skin barrier and gain access to its receptors to initiate infection." (PMID 35969080, 2022). "Especially elevated IL‐4 titers, effective even at low concentrations, may promote atopic sensitization after infection, that could be thwarted by IL‐13 expression." (PMID 36271745, 2022).
infection (continued). "Mouse models of RSV infection showed that administration of an anti-IL-33-receptor antibody that blocks the IL-33 cascade can reduce both the Th2 and Th17 environment (especially IL-13 and IL-17A) and the eosinophil recruitment induced by IL-33 after infection." (PMID 35327516, 2022). "However, when IL-4/IL-13 is deleted selectively in T cells, mice exhibit normal NB expulsion, indicating a dispensable role for T cell-derived IL-4/IL-13 in the context of NB infections but emphasizing the role for ILC2-derived IL4/IL-13 in the same setting." (PMID 36430676, 2022). "Thus, our data suggest that IL‐13 levels in sera should be included in the assessment of protective immunity due to resolved infection or vaccination." (PMID 36271745, 2022). "During extracellular pathogen infection, naïve Th cells proliferate and differentiate toward the Th2 subtype, which functions through secreting various effector cytokines, including IL-4, IL-5, IL-6, IL-10, IL-13." (PMID 35241075, 2022). "As expected, ΔILC2 mice showed evidence of increased ILC2 activity as reflected by IL-13 expression by lung ILC2s and by IL-5 expression in whole lung tissue at the peak of infection (day 7), as well as by ILC2 expansion during the resolution phase (day 14), as compared to WT mice." (PMID 34290377, 2021). "Intranasal PD1 administration post-infection decreased lung eosinophils and Il-13 expression." (PMID 34489955, 2021). "In particular, it will be important to assess whether separate or combined vaccination against IL-4 and IL-13 has any effect in models of infection with helminths." (PMID 33976140, 2021). "Mast cells release IL-25 and IL-33 in response to H. polygyrus-induced release of ATP from epithelial cells and mast cell-derived IL-33 induces ILC2 production of IL-13: both events have the potential to drive ETC hyperplasia as a response to infection with helminth parasites." (PMID 34578195, 2021). "After infection of Il13−/−, we assessed acute bleeding as well the cumulative clearance of blood." (PMID 34127548, 2021). "However, they either significantly subsided (IL-4 and IL-5) or maintained at a similar level (IL-13) in immunized mice in response to an infection with CO92." (PMID 33514747, 2021). "Overall, we found that IL-13+ ILC2s moved over greater distances post-infection." (PMID 34484215, 2021). "Previous studies using the N. brasiliensis model in IL-4Rα–deficient animals or IL-4/IL-13-double–deficient mice did not distinguish between the relative roles of IL-4 and IL-13 during infection." (PMID 34127548, 2021). "It was demonstrated that mice that lacked either IL-4 or IL-13 expression were susceptible to infection with T. muris." (PMID 34451389, 2021). "Furthermore, higher geometric mean (GM) infection intensities were observed among pupils aged ≤11, and 15 years and above with the heterozygous genotype for IL13-1055C/T (i.e. C/T), IL13-591A/G (A/G), and for IL13-1258A/G (i.e. A/G)." (PMID 34185775, 2021). "In vivo and in vitro experiments indicate, to a certain extent, that IL-13 may enhance Chlamydia replication in cell or animal models of infection." (PMID 34093528, 2021). "Finally, administration of IL-13 to mice infected with L.m favors infection control, which coincides with enhanced NK cells activation and an increase in serum IL-12 concentration." (PMID 34194428, 2021). "However, with the infection going on, type 2 immune responses (the production of cytokines such as IL-4, IL-13, and transforming growth factor β1) become predominant which can control hyper-inflammation and promote tissue repair." (PMID 35118069, 2021). "However, the expression of the anti-inflammatory cytokines IL-2, IL-10, IL-13, IL-17 was increased in the Rictor knockout mice, both at baseline and after infection, the results are in line with previous reports." (PMID 34650053, 2021).
infection (continued). "In addition, RV-C15 infection of mice with allergic airways disease had additive effects on BAL lung IL-13, IL-5 and CCL24 expression, which were greater than induced by RV-A1B." (PMID 33968043, 2021). "Although these studies establish a clear role for IL-13 in mediating type 2 immunity in the small intestine and the establishment of the adaptive immune response, very little is known about the functions of IL-13 in the earlier lung stage of this infection model." (PMID 34127548, 2021). "However, IL-13 levels in the lung lavages at day 20 post-infection were significantly elevated in the knockout mice over the wildtype controls consistent with a push toward a more intense Th2 response in the absence of Th1 and Th17 type responses." (PMID 34682248, 2021). "IL-13 alone in the absence of infection results in a loss of stemness and decreased proliferative capacity and the emergence of a highly differentiated trajectory of IECs, including goblet and tuft cells." (PMID 34283207, 2021). "Earlier, it was reported that the infection of Chlamydia leads to rapid production of IL-4/ IL-13." (PMID 34226412, 2021). "For IL-13, a significant decrease was observed in the ileum of the trickle-infected group at 21 dpi and in the jejunum of both infection groups as well as in the ileum of the trickle-infection group at 49 dpi." (PMID 34649607, 2021). "Mice lacking ILC2s due to conditional deficiency of the transcription factor RAR-related orphan receptor alpha (Rora) displayed a massive downregulation of features of type 2 immunity as reflected by reduced levels of the type 2 signature cytokines IL-4, IL-5, and IL-13 at 14 days post-infection." (PMID 32117319, 2020). "Underexpression of Th2 cytokines, such as IL4/IL13, as well as IL10 and TGFβ, which are primarily associated with tissue repair and extracellular matrix composition, was observed during the late stage of infection, especially in infected fish at 11°C." (PMID 32695119, 2020). "However, in the context of N. brasiliensis infection, iILC2s make IL-4 in addition to IL-13 at 5 days post-infection." (PMID 32793230, 2020). "However, treatment of mice with rIL-25 induces resistance to infection, concomitantly with elevated levels of IL-13." (PMID 33276813, 2020). "Repeated infections and chronic colonization by these large extracellular worms in mammals led to the evolution of type-2 immunity characterized by the production of the type-2 cytokines interleukin (IL)-4, IL-5, and IL-13." (PMID 32793230, 2020). "As the infection progresses, the immune response, modulated in part by IL-10, shifts to a mixed Th1/Th2 profile and then to a Th2 profile by 6 dpi with a significant increase of IL-4, IL-5 and IL-13 levels." (PMID 33023672, 2020). "This is consistent with data described in LCL lesions due to L. guyanensis, in which a Th2 response (IL-4 and/or IL-13) transiently predominates during the early phase of infection, followed by the development of a Th1 (IFN-γ) response during the late course of lesion development." (PMID 30810524, 2019). "There was also a decrease in IL-4, IL-6, IL-10, and IL-13 in the late stages of infection." (PMID 31192210, 2019). "However, it was shown that in cutaneous leishmaniasis due to L. guyanensis, Th2 cytokines, and particularly IL-13 are produced locally at the site of infection." (PMID 30810524, 2019). "Here we show that infection with a gastrointestinal (GI) helminth also induces a systemic innate IL-13–driven mucin-mediated protective immunity, which primes distal barrier tissue sites for subsequent secondary infections with multiple different helminth species." (PMID 31582416, 2019). "IL-4 and IL-13 increased the production further in the presence of infection (p < 0.05)." (PMID 30665337, 2019).